MUC1 (mucin 1, cell surface associated)
Diseases named in the same sentence as MUC1 in open-access papers (continued):
Sharing a sentence is not in itself a finding about the gene and the disease.
tumor (continued). "In the present study, we first analyzed the tumor and adjacent non-tumor tissues of the GC patient cohorts and the biopsy tissues of the FD patients to measure the relative mRNA expression of gastric (MUC1, MUC5AC, MUC6) and intestinal (MUC2, MUC4, MUC13) mucins." (PMID 37085819, 2023). "A Phase I clinical study revealed that gatipotuzumab was safe, well tolerated, and had clinical benefits in MUC1-positive patients with advanced solid tumors, while a Phase II clinical study showed that gatipotuzumab treatment had no obvious benefits over a placebo in tumor patients." (PMID 37489369, 2023). "However, MUC1-induced DCs did not trigger the type-1 response necessary for tumor rejection." (PMID 35883508, 2022). "Indeed, we found that incubation of primary NK cells with humanized anti-MUC1 only (without tumor cells) could induce degranulation." (PMID 34070311, 2021). "Interestingly, the cancer-associated MUC1 is hypoglycosylated, compared to the heavily glycosylated form found in normal cells, so it can be specifically targeted by CAR T cells without on-target off-tumor effect." (PMID 33737613, 2021). "Thus, knockdown of MUC1 in MDSCs may have a negative effect on the immune responses against the tumor." (PMID 34070449, 2021). "However, in this study, we focused on MUC1 in the host (but not in the tumor)." (PMID 34070449, 2021). "Indeed, our results confirmed that MUC1 was significantly lower in whether cardia or non-cardia tumor tissues than that in adjacent normal tissues." (PMID 32122390, 2020). "Along with these plausible mechanisms, mAb binding to tumor-expressed MUC1 could lead to their enhanced lysis through ADCC (antibody dependent cellular cytotoxicity) and enhanced presentation by APCs, resulting in efficient stimulation of tumor-specific T cells." (PMID 31468283, 2019). "Interestingly, binding of tumor-produced MUC1 to Siglec-9 induces negative immunomodulation." (PMID 29342882, 2018). "However, a role of MUC1 in malignant tumor growth mechanism is not elucidated yet." (PMID 29342882, 2018). "Consequently, targeting MUC1 noncirculating epitopes exclusively expressed on tumor cell surfaces could potentially bypass these limitations." (PMID 24416403, 2014). "Importantly, expression of neither MUC1.CT3 nor MUC1.CD significantly affected primary tumor mass, consistent with our finding that knockdown of MUC1 expression selectively affected metastasis but not primary tumor growth." (PMID 22586492, 2012). "Further, the significance of detection of MUC1 expression in a tumor sample is unclear, due to the fact that this may not mean that the tumor is truly negative for MUC1, patients whose tumors are not shown to be expressing MUC1 can be included into this study." (PMID 22494623, 2012). "Moreover, tumours isolated from the mouse did not express these components either, nor did they express the lineage markers MUC1 or CK14 in accordance with the pathology of the tumours, which showed no indication of differentiation but a high percentage of mitoses." (PMID 18541018, 2008). "For MUC1, among the 173 evaluable PDAC tissues (excluding 27 cases without tumor tissues or those detached from slides during IHC staining), 19% showed strong staining, 39% with moderate staining, and 40% with weak staining." (PMID 40130819, 2025).
tumor (continued). "Roughly, EGFR and MUC1 were detected on the same tumor cells in 63 (98.4%) LUAD and 76 (91.6%) CRC samples, which included samples with at least 1% of tumor cells stained positive with both EGFR and MUC1 regardless of staining intensity." (PMID 39664199, 2024). "applied immunohistochemistry on tissue microarrays and identified MUC1 and AZP1 as significant predictors of the relapse of PCa, independent of tumor grade, stage, and preoperative PSA levels." (PMID 38800374, 2024). "The CC tumor tissue and PSO exhibited negative expression of MSLN and MUC1 in the parenchymal region and positive expression of CD276." (PMID 38162496, 2023). "However, we could not manage to explore the intra-tumor heterogeneity of the MUC1 staining pattern." (PMID 37002293, 2023). "IHC staining of the tumor tissues proved that the infiltration of CD8+ T cells, but not CD4+ T cells, was significantly promoted by SZU251 + MUC1 + Al." (PMID 36499455, 2022). "Assessment of the T cell phenotype also revealed that the memory phenotype of CAR.MUC1-41BBζ and CAR.MUC1-CD28ζ after coculturing with MUC1+ tumor cells was not significantly differed." (PMID 36457849, 2022). "While another anti-MUC1 antibody, MA5, stained several normal tissues (e.g., pancreas, colon, stomach, lung) and many tumour tissues, PAM4 did not, confirming its PDAC specificity." (PMID 35892707, 2022). "In fact, CAR-T cells directed against MUC1 and PSCA are not able to completely eliminate solid tumors, and tumor cells expressing low densities of the target antigen are the main reason for tumor escape." (PMID 35924243, 2022). "Immunohistochemically, tumor cells were positive for Vimentin (mesenchyme), CK7, CK19, MUC-1, MUC-5AC, MUC-6, S-100p (focal), Ki-67 (12%), and negative for Inhibin-α, ER, CK20, CEA, and MUC-2." (PMID 33592896, 2021). "There are many tumor markers on HCC cells that have not been yet targeted, such as EGFR, FGFR, PDGFR, MUC1, and mesothelin." (PMID 34679012, 2021). "Both MUC1 and TFF2 expression showed a slight decreased in cardia tissue compared with non-cardia tumor tissue, but there were no significantly differences." (PMID 32122390, 2020). "This study confirmed the expression of MUC5AC and MUC6, as well as negative expression of MUC1 and MUC2 throughout the tumour, with the final diagnosis indicating mucin producing HCC." (PMID 30875782, 2019). "TAA is not unique to tumor tissue as it is also present in normal tissues; it is highly expressed in proliferating tumor cells expressing HER2, MART-1, MUC1, and MAGE." (PMID 31443694, 2019). "In MUC1-positive A549 cells, BBiApt significantly enhanced CD16-positive cells’ cytotoxicity against tumor cells, while MUC1 aptamers or CD16 aptamers alone failed to generate a similar effect." (PMID 30699986, 2019). "Tumor cells were strongly and diffusely positive for CK7, CK19, MUC1 and negative for CK20, CDX‐2, MUC2." (PMID 31102323, 2019). "Although some antigens have been discovered that are very tumor selective (e.g., MUC1, EGFRvIII, CEA, GD2 ganglioside, PSCA), essentially no antigens have been discovered that are absolutely restricted to tumor cells." (PMID 31544847, 2019). "Despite complete surgical extirpation of tumor and the addition of PDE5 inhibition and MUC1/PolyICLC vaccination, however, no such dramatic clinical benefit was detected." (PMID 31214178, 2019). "In both the OVCAR3 and OV90 models, tumor recurrences at early time points following CAR T cell treatment were TAG72 low/negative, but maintained MUC16 and/or MUC1 expression." (PMID 30510550, 2018). "Similar to Muc1-Bi-1, Muc1-Bi-2 exhibited no cell killing for Muc1 negative CHO cells, but potent immune cell dependent cell killing against Muc1 positive tumor cells." (PMID 29357376, 2018).
tumor (continued). "Tumor with pseudoglandular pattern was positive for Heppar-1, GPC-3, but negative for CK7, CK19, and MUC-1." (PMID 29504997, 2018). "Although the remaining eight WT1-mutant tumours lacked WT1 protein expression, MUC-1 was consistently positive in UB-like structures." (PMID 29040332, 2017). "Intriguingly, PAR-1 expression did not correlate to epithelial (tumor) cell markers Epithelial cell adhesion molecule (EpCAM), Cadherin 1 (CDH1) and Mucin 1 (MUC1)." (PMID 28173772, 2017). ", we detected a highly significant SF-1 overexpression in the pediatric ACC tumor model SJ-ACC3 (348.2± 27.4%, p < 0.001 vs. MUC-1) and almost no detectable SF-1 expression in SW-13 xenografts (0.03± 0.0%, p < 0.001vs." (PMID 27764813, 2016). "Tumor and non-tumor samples differed significantly in the expression of 10/22 genes: CCNB1, CLDN4, CLDN6, MMP2, MUC1 (all: p < 0.05), BAG1, SERPINB3 (all: p < 0.01), CD44 (standard variant), MKI67, and MYBL2 (all: p < 0.001)." (PMID 27542596, 2016). "Immunophenotypically, the tumor cells were strongly positive for CK7, CK19, CA19.9, and MUC1 but negative for other lineage markers, findings suggestive of pancreatobiliary type differentiation." (PMID 27999702, 2016). "However, vaccines containing conjugated or unconjugated MUC1 peptides, plus various adjuvants, failed to induce therapeutic tumor-specific CTLs in vivo, which may be due to protein conformational dissimilarities, improper vaccine formulations, and inadequate adjuvants." (PMID 26417929, 2015). "Our results confirm that anti-MUC1 SP antibodies not only bind MUC1-positive tumor cells and MM patient-derived PC, but also effectively mediate CDC of both solid and haematological MUC1-positive tumor cells lines, but not of NHEC." (PMID 24416403, 2014). "FACS analyses to assess fusion cells demonstrated that DCs expressed CD11c molecules and were negative for Muc-1 tumor antigen, whereas MDA-MB-231 expressed Muc-1 tumor antigens and were negative for CD11c molecule." (PMID 25036145, 2014). "The ethanol-treated and untreated tumor cells (PANC/Mock and PANC/TGF-β) showed sustained expression of HLA-ABC, HLA-A2, MUC1, TLR2, and TLR4, but not HLA-DR, CD80, CD86, and CD83 (data not shown)." (PMID 23717436, 2013). "In this report, tumor cells showed positive reaction for E-ca, CDX2 and MUC1, and negative reaction for MUC2, Hep Par1 and TTF-1." (PMID 23938020, 2013). "Here, we demonstrate a requirement for MUC1 in carcinoma cell metastasis dependent on EGFR and Src without affecting primary tumor growth." (PMID 22586492, 2012). "The survival rates were not significantly different when patients had or had no expression of MUC1, MUC2, MUC5AC, or MUC6 in tumor." (PMID 22027009, 2011). "In order to further confirm the immune responses to be tumor Ag-specific, not mouse-self Ag-specific, we used an exogenous MUC1 (human MUC1) to generate the LLC-MUC1 cell line." (PMID 21931708, 2011). "Whereas CK20 was non-significant, MUC1 expression in ≥40% of tumour cells (P = 0.038) and MUC4 expression in any tumour cell (P = 0.029) each significantly predicted a poor prognosis." (PMID 19236510, 2009). "Thus, 10 μg per injection of MUC1-pep-STn or MUC1-prot-STn could induce humoral responses in MUC1 transgenic mice but at the concentration and in the model used here this did not result in consistent protection from tumour challenge." (PMID 19436292, 2009). "MUC1 expression was evaluated by immunohistochemistry stratifying samples according to staining intensity as tumor with high MUC1 expression (MUC1H; ≤ 50% positive tumor cells), tumor with low MUC1 expression (MUC1L; 50 − 20% positive tumor cells), and tumor that do not express MUC1 (MUC1neg)." (PMID 41533164, 2026). "In addition, in YBX1 knockout tumour cells, replenishment of NLS-YBX1 but not NES-YBX1 upregulated MUC1 and MUC13." (PMID 35292781, 2022).
tumor (continued). "If we extend the marker genes to include the non-classical ones such as MUC1 for ADC, SOX2 for SCC, and ASCL1 for NET, the mixed-lineage cancer cells were notably observed in all of the sixteen patients from whom we isolated epithelial cells in tumor tissues." (PMID 35962452, 2022). "Interestingly, the non-glycosylated MUC1 protein was incapable of binding to the MGL receptor, which further highlights the importance of tumor cell surface glycan modifications." (PMID 36686742, 2022). "Moreover, the platform responded selectively to tumor cells, showing higher toxicity against MUC-1-positive tumor cells (HT-29 and MCF-7) compared to MUC-1-negative cells (Hep-G2)." (PMID 33668271, 2021). "Furthermore, other tumor specific antigens (TSA), such as Mucin 1 (MUC1), which is absent in normal tissues but overexpressed in almost all human epithelial cell malignancies, should be investigated in QDs targeting applications." (PMID 34745974, 2021). "Conversely, in MUC-1, RGZ did not modulate the CXCL12/CXCR4 axis, suggesting that the up-regulated CXCL12 in response to RGZ might be active only in the primary tumor but not in the metastatic cells." (PMID 34834449, 2021). "The tumor cells were positive staining for Heppar1, and negative staining for CK7, CK19, and Muc-1." (PMID 29504997, 2018). "In earlier studies, MUC1 was shown to be targeted by non-classical MHC-unrestricted CTLs, based on their generation upon sequential stimulation by MHC-unmatched MUC1+ tumor cell lines and blocking of tumor cell killing by anti-MUC1 antibody." (PMID 30405607, 2018). "For example, OVCAR8 (derived from primary tumour in the ovary), SKOV3 (derived from ascitic fluid) and EFO27 (derived from omentum metastasis) presented the same immunophenotype without expression of MUC16, MUC1, Tn, STn, and T." (PMID 30011875, 2018). "However, neither enzalutamide nor abiraterone improved PC-3 cells' sensitivity to MUC1-specific CTL-mediated lysis relative to vehicle-treated tumor cells." (PMID 25344864, 2014). "The tumor cells were diffusely positive for CK7 and MUC1 and negative for MUC2 and HER2-neu." (PMID 24367734, 2013). "For ICAM1, IGSF4, EHM2, CLDN1 and MUC1, no methylation was detected in 20 sporadic RCC tumours." (PMID 18195710, 2008). "Analysis of MUC1 expression was possible in 403 of the 462 tumours on the TMA (87%), with the remainder being lost during antigen retrieval or not demonstrating viable tumour cells within the core." (PMID 17349047, 2007). "No statistical correlation was found between MUC1-CIC and tumor or sera MUC1 expression." (PMID 17064405, 2006). "MUC1 and MUC2 mucins were not simultaneously expressed in tumour cells." (PMID 14760390, 2004). "Although in vitro detection of cytolytic activity does not always correlate with in vivo tumour rejection, the potential of the C595scFv-Fc-IL2 fusion protein to activate immunocompetent resting NK and preactivated T cells after binding to MUC1-positive tumour cells is clearly demonstrated." (PMID 12966437, 2003). "In MUC1-positive tumours, MHC class I expession is frequently downregulated and MUC1-specific cytotoxic T cells (CTLs) are either not available or in a state of anergy allowing tumour growth without limitation by CTL control." (PMID 12966437, 2003). "Noticeably, overexpressed NYESO1 (CTAGB1), MUC1, MAGEA3, MAGEA4, or CEA (CEACAM5) antigens did not correlate with TERT improved PFS of patients with high B cell infiltrate, suggesting a selective role of TERT over other common tumor antigens in driving local antitumor immunity." (PMID 36909826, 2023). "The expression levels of mucin 1 (MUC1), epidermal growth factor receptor (EGFR), epithelial cell adhesion molecule (EpCAM), and extracellular matrix metalloprotease inducer (EMMPRIN) in tumor-derived MVs were used to distinguish cancer patients from healthy controls regardless of tumor type." (PMID 33499132, 2021).
tumor (continued). "An approach using synthetic MUC1 VNTR peptides of various lengths, conjugated to carriers, such as keyhole limpet hemocyanin(KLH), bovine serum albumin (BSA), and diphtheria toxin(DT) failed to induce effective antitumor responses, especially tumor-specific CTLs." (PMID 26417929, 2015). "Consequently, Tn glycans on MUC1 that bind MGL might instruct DC to drive Th2-mediated responses, which, unlike those of Th1 effector cells, are thought not to contribute to tumor cell eradication." (PMID 26343966, 2013). "Finally, there are ongoing studies of Tumor lysate-based DC vaccines, which demonstrated an early invitro efficacy, while MUC1-loaded DC vaccine used as adjuvant treatment after the resection of biliary tract and pancreatic malignancies did not exert anti-MUC-1 antibody responses." (PMID 35743107, 2022).